PGR (progesterone receptor)
Diseases named in the same sentence as PGR in open-access papers (continued):
Sharing a sentence is not in itself a finding about the gene and the disease.
soft tissue sarcoma (2 papers, 2011 to 2013). A malignant neoplasm arising from muscle tissue, adipose tissue, blood vessels, fibrous tissue, or other supportive tissues excluding the bones. "The purpose of this study is to clarify the prognostic significance of expression of Skp2 related to gender, estrogen receptor (ER) and progesterone receptor (PGR) in soft tissue sarcomas (STS)." (PMID 23497154, 2013).
urothelial carcinoma (2 papers, 2022 to 2025). A malignant neoplasm derived from the transitional epithelium of the urinary tract (urinary bladder, ureter, urethra, or renal pelvis). "Urothelial carcinoma could express both GATA3 and ER, but not GDFP-15 and mammoglobin, so the standard panel for differential diagnosis includes all of them, associated with PgR." (PMID 36248976, 2022).
uterine adenosarcoma (2 papers, 2007 to 2019). "In uterine adenosarcoma lacking sarcomatous overgrowth, we documented that in 18 out of 20 (90%) of the cases either the oestrogen or the progesterone receptor stained positive in the sarcomatous component." (PMID 17895898, 2007).
acinic cell carcinomas of (1 paper, 2022). "It is morphologically similar to acinic cell carcinomas of salivary glands and pancreas and has a triple-negative phenotype (estrogen receptor-negative, progesterone receptor-negative, and Her-2/neu negative)." (PMID 36332545, 2022).
acoustic neuroma (1 paper, 2009). A type of benign brain tumor that begins in the Schwann cells, which produce the myelin that protects the acoustic nerve - the nerve of hearing. "Since the progesterone receptor was expressed in all acoustic neuroma samples, they advocated further studies to find out about the inhibitory effect of antiprogesterone treatment on acoustic neuroma growth, which may be important particularly in elderly people or high-risk patients." (PMID 19889208, 2009).
acute kidney injury (1 paper, 2017). Sudden and sustained deterioration of the kidney function characterized by decreased glomerular filtration rate, increased serum creatinine or oliguria. "Following NTS, both control and pGR KO mice developed severe acute kidney injury (AKI) and nephrotic syndrome, as evidenced by approximately a three-fold increase in serum creatinine, and hypoalbuminemia, respectively." (PMID 28852159, 2017).
adrenal pheochromocytoma (1 paper, 2017). "mPRβ mRNA was drastically increased during NGF-induced neurogenesis in PC12, a rat adrenal pheochromocytoma cell line, whereas the expression of other progesterone receptors such as mPRα, Progesterone Receptor (PR), and PGRMC-1 did not exhibit the same expression profile." (PMID 28701790, 2017).
alcohol dependence (1 paper, 2020). Physical and psychological dependence on alcohol. "Based on the importance of GR activity in both alcohol dependence and pain, we also examined GR phosphorylation (pGR) as a marker of stress-related glucocorticoid signaling." (PMID 33005820, 2020).
anaplastic meningioma (1 paper, 2021). A WHO grade III meningioma characterized by the presence of malignant morphologic features, including malignant cytology and a very high mitotic index (20 or more mitoses per ten high power fields). "Immunohistochemically, there was a strong expression of Epithelial Membrane Antigen (EMA) and Vimentin (not shown), while the progesterone receptor (PR) was focally positive (<10%), as is usual in anaplastic meningiomas that do not usually have a positive expression of PR." (PMID 34562970, 2021).
angiosarcoma (1 paper, 2024). A malignant tumor arising from the endothelial cells of the blood vessels. "Immunohistochemical profiling is essential for differentiating PASH from low-grade angiosarcoma, with specific markers such as CD34, vimentin, desmin, actin, and progesterone receptor aiding in the correct diagnosis and preventing misinterpretation." (PMID 39564024, 2024).
appendiceal adenocarcinoma (1 paper, 2019). "The appendiceal adenocarcinoma also showed positive immunoreaction for CK7, CK20, CDX-2, and SATB2 but was negative for estrogen receptor, progesterone receptor, Pax-8, CD56, synaptophysin, and chromogranin A." (PMID 31409389, 2019). "Both the appendiceal adenocarcinoma and malignant components of the OMT stained positive for CK7, CK20, CDX-2, and SATB2 but negative for estrogen receptor, progesterone receptor, and pax-8." (PMID 31409389, 2019).
Arthritis (1 paper, 2020). Inflammation of a joint. "Mice lacking progesterone receptor signaling in the osteoprogenitor cells were more susceptible to collagen-induced arthritis, especially male mice." (PMID 32616012, 2020).
basal cell carcinoma (1 paper, 2015). A carcinoma involving the basal cells. "For example in MRC-5 fibroblasts, genes PGR and ADH1B belonging to pathways “Oocyte meiosis” and “Propanoate metabolism” were the only genes which were up-regulated and Wnt16 belonging to “Basal cell carcinoma” pathway was the only gene which was down-regulated with a log2 fold change >1." (PMID 26380578, 2015).
benign adenomas (1 paper, 2021). "Finally, one study demonstrated high levels of progesterone receptor (PR) in the human adrenal cortex that was further increased in benign adenomas, and isolated PPNAD nodules." (PMID 34063067, 2021).
Breast hypertrophy (1 paper, 2022). The presence of hypertrophy of the breast. "In this study we focused on analyzing aromatase gene polymorphisms and progesterone receptor gene polymorphism in women with gigantomastia." (PMID 35160095, 2022). "The aim of this study was to identify genetic risk factors for breast hypertrophy among genes for aromatase (CYP19A1) and progesterone receptor (PGR), examining their single nucleotide polymorphisms (SNPs) (CYP19A1: rs749292 and rs7172156 and PGR: rs1042838)." (PMID 35160095, 2022). "In this study we examined the association of genetic variants of progesterone receptor (PGR) and aromatase (CYP19A1) genes with gigantomastia risk." (PMID 35160095, 2022). "The results are preliminary and provide rationale for further studies examining PGR and CYP19 polymorphisms in women with gigantomastia, e.g., also including intron 4 (TTTA)n repeat and TCT deletion/insertion polymorphisms." (PMID 35160095, 2022). "However, there are still many unverified hypotheses concerning breast hypertrophy etiology, e.g., abnormal sensitivity of estrogen (ER) or progesterone receptors (PGR) or aromatase overexpression." (PMID 35160095, 2022).
breast NETs (1 paper, 2020). "Metastases to the breast from NENs of other organs can be distinguished through IHC: Cheratin 7, estrogen (ER) and progesterone receptors (PgR), GATA3 and Gross cystic disease fluid protein 15 (GCDFP15) are quite typical for breast NETs." (PMID 33584543, 2020).
cavernous hemangioma (1 paper, 2020). A hemangioma characterized by the presence of cavernous vascular spaces. "In addition, the progesterone receptor is present in the orbital cavernous hemangioma, implying a hormone-dependent mechanism in tumor growth." (PMID 32702816, 2020).
cervical squamous cell carcinoma (1 paper, 2019). A squamous cell carcinoma arising from the cervical epithelium. "In the case of cervical squamous cell carcinoma, alteration frequency was greatest in MME (10%), followed by PGR (9%) and AGTR1 (8%)." (PMID 31879572, 2019). "Three genes (MME, PGR, and AGTR1) showed >7% alteration frequency in the TCGA cervical squamous cell carcinoma." (PMID 31879572, 2019).
chondrosarcoma (1 paper, 2021). A malignant cartilaginous matrix-producing mesenchymal neoplasm arising from the bone and soft tissue. "Five cases harbored driver gene fusions, including a novel fusion involving the progesterone receptor (PGR) in a patient who developed chondrosarcoma during pregnancy and had an exceptional response to tamoxifen." (PMID 33630025, 2021).
Chordoid Meningioma (1 paper, 2018). A WHO grade II, usually recurring meningioma characterized by the predominance of tissues that are histologically similar to chordoma. "Whether KLF4 and/or the progesterone receptor that appears to be highly expressed in secretory and chordoid meningioma (MM Georgescu, unpublished observations) play a role in NHERF1 upregulation remains to be investigated." (PMID 29983887, 2018).
chorioamnionitis (1 paper, 2022). A morphologic finding indicating inflammation of the fetal sac membranes. "In addition, IL-1β is a potent inhibitor of decidual cell progesterone receptor expression, which accompanies chorioamnionitis." (PMID 35464466, 2022).
congenital hyperinsulinism (1 paper, 2018). "SLC37A1 seems to be required for lipid biosynthesis in cancer cell lines, SLC37A2 has been proposed as a vitamin D and a phospho-progesterone receptor target gene, while mutations in the SLC37A3 gene appear to be associated with congenital hyperinsulinism of infancy." (PMID 29719821, 2018).
crescentic glomerulonephritis (1 paper, 2017). A histopathologic term for a pattern of diseases characterized by extensive crescent formation in the glomeruli; patients present clinically with rapid deterioration of renal function, and possible progression to end-stage renal failure within weeks or months. "However, pGR KO and Pax8-Cre GR KO mice appear to differ in that the crescentic glomerulonephritis induced by NTS is clearly worsened in pGR KO and attenuated in Pax8-Cre GR KO mice." (PMID 28852159, 2017). "Here we report for the first time that the podocyte GR plays a protective role in the glomerular filtration barrier in vivo in the setting of acute systemic injury (LPS) and in crescentic glomerulonephritis (NTS), as evidenced by worsening proteinuria and podocyte injury in pGR KO mice." (PMID 28852159, 2017).
cystic tumors (1 paper, 2019). "When it is difficult to use HE staining to evaluate ovarian-like stroma, staining the cystic tumor using PgR is required or the use of multiple tools such as PgR plus ER." (PMID 31338648, 2019). "MCNs have ovarian-like stroma that is strongly immunostained for ER, PgR, and inhibin, but the other cystic tumors are not stained." (PMID 31338648, 2019).
dependent (1 paper, 2005). "In the present study using nontreated primary tumours, sVEGFR-1 levels were significantly higher in PgR-negative tumours rather than PgR-positive tumours, which seems to support the idea that sVEGFR-1 is downregulated in purely hormone-dependent tumours such as ER-positive and PgR-positive tumours." (PMID 15668703, 2005).
eccrine carcinoma (1 paper, 2012). An adenocarcinoma with eccrine differentiation arising from the sweat glands. "It is known that apocrine-eccrine carcinomas often express estrogen receptor and progesterone receptor." (PMID 23056620, 2012).
fibroma (1 paper, 2024). A non-metastasizing neoplasm arising from the fibrous tissue. "Immunohistochemistry revealed strong positivity for smooth muscle actin (SMA), inhibin, and progesterone receptor (PR), along with negative staining for desmin and caldesmon, and the distinct staining pattern of reticulin further supports the diagnosis of a benign cellular fibroma." (PMID 39553140, 2024).
Follicular Cyst (1 paper, 2023). Cyst due to the occlusion of the duct of a follicle or small gland. "Our data also showed that the mRNA expressions of ESR1, ESR2, PGR, IGF1Rs and GHSR were changed in follicular cysts." (PMID 37958056, 2023).
Fulminant hepatic failure (1 paper, 2021). Hepatic failure refers to the inability of the liver to perform its normal synthetic and metabolic functions, which can result in coagulopathy and alteration in the mental status of a previously healthy individual. "We report herein a case of a woman with iciHHV-6A+ and iciHHV-6B+, who developed ulipristal acetate (a selective progesterone receptor modulator)-induced fulminant hepatic failure that required liver transplantation." (PMID 35062266, 2021).
fungal infection (1 paper, 2023). "Among these pathways, the PDGF BB and PGR pathways were predicted to be activated by fungal infection, and experiments with small-molecule inhibitors indicated that these pathways governed the endocytosis of A. fumigatus in an additive manner." (PMID 37255456, 2023).
gallbladder carcinoma (1 paper, 2012). "Given the potential hormonal role in gallbladder diseases, and also the previously explored role of ESR/PGR polymorphisms in female related cancers, we hypothesized that genetic variants in ESR1, ESR2 and PGR genes may have significant impact on the risks of gallbladder cancer." (PMID 22808109, 2012).
glomerulonephritis (1 paper, 2017). A renal disorder characterized by damage in the glomeruli. "As expected, histology revealed crescentic glomerulonephritis in both control and pGR KO mice." (PMID 28852159, 2017).
hamartoma (1 paper, 2025). A benign and excessive tumor-like growth of mature cells and normal tissues which grow in a disorganized pattern. "Estrogen receptor (ER) and progesterone receptor (PR) expression in hamartomas is similar to that in normal breast tissue epithelium." (PMID 40724578, 2025).
Headache (1 paper, 2023). Cephalgia, or pain sensed in various parts of the head, not confined to the area of distribution of any nerve. "However, when divided according to the headache diagnosis, the correlation persisted only for PgR in MWOA." (PMID 37189678, 2023). "When considering the burden of headaches in both M and TTH, we found that the frequency of headache attacks was positively correlated with female HR expression in BC malignancies, although less for estrogen (ER) (r = 0.11, p = 0.05) than progesterone (PgR) (r = 0.15, p = 0.007)." (PMID 37189678, 2023).
hereditary cancer (1 paper, 2008). Malignant neoplasms occurring in families at a rate greater than that expected by chance and caused by germline mutations in a specific gene. "Out of the hereditary cancer patients in our study group, 75% were found to be triple-negative, lacking ERα, PgR and HER-2 over-expression." (PMID 18405391, 2008).
Hernia (1 paper, 2025). "Inhibition of P4/PGR signaling prevents exogenous E2- plus P4-induced hernia development in WT mice." (PMID 40504614, 2025). "Our findings, along with the positive correlation between ESR1, PGR, and Ki-67 expression in human stromal hernia tissue, highlight both a role for P4/PGR signaling and a potential use for PGR antagonists in men." (PMID 40504614, 2025). "To determine the mechanisms through which P4/PGR signaling causes LAM fibrosis, muscle atrophy, and hernia development, we performed snRNA-seq of the LAM of WT mice after 10 weeks of treatment with Veh, EP, and E2 plus P4 plus RU486 (EPR)." (PMID 40504614, 2025). "Inhibition of P4/PGR signaling prevents hernia development and delays further hernia enlargement in Aromhum mice." (PMID 40504614, 2025). "Collectively, these findings illustrate the complex processes that contribute to LAM fibrosis and establish PGR signaling as a driver of hernia development as well as a potential target for pharmacologic management of inguinal hernia." (PMID 40504614, 2025). "We sought to define the role of P4/PGR signaling in hernia development by administering E2 and/or P4 to WT mice for 12 weeks starting at 8–10 weeks of age." (PMID 40504614, 2025). "While the Aromhum hernia model has been used previously to establish the role of E2/ESR1 signaling in LAM fibroblast activation, this study furthers our understanding of hernia pathogenesis by implicating P4/PGR signaling as an important downstream regulator of E2/ESR1-induced LAM fibrosis." (PMID 40504614, 2025). "Taken together, these results demonstrate the central role of P4/PGR signaling in LAM fibrosis, atrophy, and hernia development, while also confirming that the attenuating effects of RU486 treatment are mediated by P4/PGR." (PMID 40504614, 2025). "Effect of E2/ESR1-induced PGR expression on LAM fibroblast proliferation in Aromhum mice and human hernia tissue." (PMID 40504614, 2025). "Taken together, the results from these experiments suggest that inhibition of PGR signaling in LAM fibroblasts prevents hernia development and stalls established hernia growth by attenuating LAM fibrosis and muscle atrophy." (PMID 40504614, 2025).
hydrocele (1 paper, 2024). "Pathological examination revealed closely-located two cysts; larger one was infected hydrocele testis, and smaller one was epithelial cyst, which were immunohistochemically positive widely for estrogen receptor (ER) and partly for progesterone receptor (PR)." (PMID 38681548, 2024).
Hyperkalemia (1 paper, 2023). An abnormally increased potassium concentration in the blood. "Noteworthy, Spi is a potent FDA-approved MR antagonist, however, less selective because it causes anti-androgenic (via AR) and progestogenic (via progesterone receptor, PR) side effects as well as hyperkalemia." (PMID 37578563, 2023).
Inguinal hernia (1 paper, 2025). Protrusion of the contents of the abdominal cavity through the inguinal canal. "We also sought to determine whether the positive correlation between ESR1 expression, PGR expression, and fibroblast proliferation was present in the abdominal muscle of human patients with inguinal hernias." (PMID 40504614, 2025).
injury (1 paper, 2019). Damage inflicted on the body as the direct or indirect result of an external force, with or without disruption of structural continuity. "Moreover, administration of progesterone improved brain function through reducing BBB permeability and increasing occludin expression in rats with traumatic brain injury, and progesterone receptor antagonist directly inhibited these functions." (PMID 31182728, 2019).
insulinoma (1 paper, 2025). "Specifically, the membrane progesterone receptor component PGRMC1 has been reported to cross-talk with and enhance GLP-1-induced insulin secretion in a rat insulinoma cell line." (PMID 40002193, 2025).
intestinal polyposis (1 paper, 2011). "To analyze the influence of systemic progesterone receptor signaling, we crossed mice that lacked the progesterone receptor (PRKO) to the ApcMin/+ mouse, a model for spontaneous intestinal polyposis." (PMID 21818351, 2011).
intracranial meningioma (1 paper, 2022). A meningioma that arises within the cranial cavity. "It was found that intracranial meningiomas with higher progesterone receptor expression have significantly lower MIB-1 indices." (PMID 35205781, 2022).
intrauterine growth restriction (1 paper, 2024). "Our results are consistent with knockout studies where selective disruption of progesterone receptor signaling in immune cells causes damage to the placenta, intrauterine growth restriction, and fetal wasting in the absence of infection." (PMID 38190129, 2024).
ischemic stroke (1 paper, 2023). A stroke disorder caused by obstruction of blood flow to the brain, due to thrombotic (local blood clot formation) or embolic (due to a blood clot or other material traveling from another site) event. "The critical role of the progesterone receptor in brain injury is highlighted in ischemic stroke where neuroprotection is reduced in neuron-specific progesterone receptor conditional knockouts." (PMID 37653253, 2023).
lactic acidosis (1 paper, 2009). Metabolic acidosis characterized by the accumulation of lactate in the body. "Using SSS we find that the highly scoring regression models for PgR status involve the ER factor in addition to Lactic Acidosis factor 10 – we label this the PgR specific factor." (PMID 19225561, 2009).
luminal B breast carcinoma (1 paper, 2021). A biologic subset of breast carcinoma defined by low to moderate expression of genes characteristic of luminal epithelial cells including estrogen receptor (ER), and high expression of GGH, LAPTM4B, and CCNE1. "Luminal B breast cancer is hormone-receptor positive (estrogen-receptor and/or progesterone-receptor positive), and either HER2 positive or HER2 negative with high levels of Ki-67." (PMID 34660251, 2021).
lung diseases (1 paper, 2024). "In addition to PGR, several steroid hormone receptors have been reported to affect COPD or other lung diseases." (PMID 39138434, 2024).